ENSG00000201516
Synonyms: LOC124900182
Gene: Small nucleolar RNA gene on chromosome 4 (176,098,163 to 176,098,285, forward strand). Ensembl gene ENSG00000201516.
Gene Ontology:
Biological process: RNA processing
Cellular component: nucleolus
Homologues: Paralogues in human: SNORA51 (82% identical).